AHI1-DT (AHI1 divergent transcript)
Synonyms: C6orf217; LINC00271; NCRNA00271
Gene: Long non-coding RNA gene on chromosome 6 (135,497,422 to 135,894,890, forward strand). Ensembl gene ENSG00000231028.
Diseases named in the same sentence as AHI1-DT in open-access papers:
AHI1-DT is named in the same sentence as 1 disease in open-access papers, as found by Europe PMC text mining. Sharing a sentence is not in itself a finding about the gene and the disease.
AHI1-DT shares sentences with these, for which no sentence is quoted: asthma (1 paper).